ROS1 (ROS proto-oncogene 1, receptor tyrosine kinase)
Diseases named in the same sentence as ROS1 in open-access papers (continued):
Sharing a sentence is not in itself a finding about the gene and the disease.
cancer (continued). "Hyper-methylation of promoter and copy number gain of ROS1 were reported as one of the mechanisms that activate ROS1 expression in fusion-negative carcinomas." (PMID 30943926, 2019). "Thus, the results of the present study showed that LIX1L and the modifying kinase, ROS1, can be exploited as potential targets in LIX1L-expressing cancers." (PMID 26310847, 2015). "Based on the mutation profiles in three genes (ROS1, SPEN, and PTPRT), we defined the TMB prognostic score that could predict cancer survival prognosis in the immunotherapy setting but not in the non-immunotherapy setting." (PMID 36911742, 2023). "The results of the driver gene detection for EGFR, ALK, and ROS1 in cancer cells from peripheral blood samples were negative (May 15, 2021)." (PMID 35029237, 2022). "Subsequent study of molecular markers in cancer cells (ALK, ROS1, EFGR mutations) were negative." (PMID 30986912, 2019). "Cancers of adrenal (7/10 cancer samples expressed TRK-A), pancreas (5/17 TRK-A), ovary (7/20 TRK-A), esophagus (9/20 TRK-A and ROS1), urinary bladder (6/22 TRK-A), and endometrium (9/17 ROS1) expressed increased levels of TRK-A and/or ROS1, compared to corresponding normal samples." (PMID 24386191, 2013). "Sequencing data for ROS1 and RASAL1 genes were retrieved in silico from WES analysis of 197 Italian subjects with no reported cancer history, who were selected as controls." (PMID 32906649, 2020). "We identified new gene fusions involving ROS1, SLC1A2, RAF1, EWSR1, CDK6, and CLTC, some occurring in cancer types not previously known to harbor fusions." (PMID 23637631, 2013). "Our results, therefore, suggest that the drug Entrectinib may be a choice in the treatment regimen of a diverse number of cancer types but may not be beneficial to patients diagnosed with STES, BLCA, LUSC (apart from ROS1-positive) and PRAD." (PMID 32152446, 2020). "Finally, as reported in Asian studies, ROS1 and RET fusion genes were found in large cell and not otherwise specified carcinoma highlighting that the screening should not be restricted to adenocarcinoma." (PMID 28881815, 2017). "Based on our above findings of p-FAK upregulation under ROS1 inhibitor resistance, we next tested whether inhibiting FAK activity could restore the negative impact of ROS1 inhibitors on cancer cell proliferation in vitro using CTG assays in the five CDH1-deficient cell lines." (PMID 37324948, 2023). "Interestingly, ROS1 and BRD4 KGFs occur at four different breakpoint sites; conversely, ALK and RET are found rearranged using the same breakpoint in different cancer cell line models, regardless of the cancer type context." (PMID 33257674, 2020). "Moreover, although the expression of ALK and ROS1 at the C-terminus was very limited in all fusion-negative cancer cells, the expression or phosphorylation of C-terminal RET was markedly elevated in 2 of the 36 RET fusion–negative cancer cells." (PMID 30943926, 2019).
adenocarcinoma (117 papers, 2012 to 2025). A common cancer characterized by the presence of malignant glandular cells. "The mutation of the BRAF gene, like the rearrangement of the ROS1 gene, is most often detected in patients with adenocarcinoma." (PMID 40076671, 2025). "EGFR mutations, ALK, and ROS1 translocations were identified almost exclusively in patients with adenocarcinoma in line with reported scientific literature." (PMID 39512773, 2024). "Repeat liver biopsy showed retained adenocarcinoma histology and persistent loss of ROS1 expression by IHC." (PMID 37923925, 2023). "Patients with stage IIIb/IV adenocarcinoma with ROS1 rearrangement, EGFR mutations, or ALK rearrangement were retrospectively identified." (PMID 33005033, 2020). "ROS1-rearranged adenocarcinomas appeared as solid tumors and were associated with young age, pericardial metastases and advanced nodal metastases relative to tumors with EGFR mutations or ALK rearrangement." (PMID 33005033, 2020). "Positive ROS1 IHC-staining was strongly associated with adenocarcinomas." (PMID 37237384, 2023). "In adenocarcinoma, tyrosine kinase inhibitors were developed for EGFR mutations and ALK and ROS1 translocations and were approved for use in the treatment of advanced stage adenocarcinomas." (PMID 40076671, 2025). "It is also advised that ROS1 testing be conducted for all patients diagnosed with adenocarcinoma, and BRAF testing should be considered for patients with metastatic non-squamous NSCLC or NSCLC NOS." (PMID 41153394, 2025). "ROS1 rearrangements were also more frequent in adenocarcinomas (8.2%) vs. the other subtypes (p = 0.023)." (PMID 40867330, 2025). "Guidelines recommend testing for driver mutations (e.g., EGFR, ALK, ROS1) in advanced NSCLC, particularly adenocarcinoma." (PMID 39429333, 2024). "Genetic variations that are frequently detected in adenocarcinoma include EGFR, ALK, and ROS1 mutations." (PMID 39685930, 2024). "In particular, ROS1 should be sought not only in adenocarcinomas, but also in tumors with mixed histology or squamous-cell carcinomas, because an adenocarcinoma component cannot be excluded, especially in never-smokers or younger (<50 years) patients." (PMID 37511255, 2023). "In fact, ROS1 rearrangements are more frequently found in adenocarcinomas (with a predominance of solid, papillary, acinar, cribriform, and mucinous histology patterns), women, young patients and light- or never-smokers." (PMID 37511255, 2023). "Most prevalent actionable mutations in adenocarcinoma include KRAS, EGFR, ALK, RET, ROS1, BRAF, HER2, MET." (PMID 37301854, 2023). "When we analyzed individual genes, both ALK and ROS1 fusion patients still had a higher PD-L1 positive rates than wild type adenocarcinoma patients." (PMID 35980949, 2022). "Several studies have indicated that ROS1 translocation usually occurs in EGFR wild-type adenocarcinomas." (PMID 35628598, 2022). "Surprisingly, in this series 92% of cases were adenocarcinoma and KRAS mutation and ROS1 rearrangement was reported in 7 cases and 1 case, respectively." (PMID 35842660, 2022). "Similar features have also been reported for ROS1 alterations, which, in addition, are more often found in advanced stage adenocarcinomas." (PMID 33435440, 2021). "Our study showed that in a cohort of patients with advanced adenocarcinomas, patients with ROS1-rearranged tumors exhibit characteristic clinical and radiologic features compared to those with EGFR mutations or ALK rearrangement." (PMID 33005033, 2020). "Conversely, NKX2-1 and mucins (MUC1, MUC5B) were more highly expressed in adenocarcinoma, as were ROS1 and CLDN3." (PMID 32381040, 2020). "ROS1 rearrangement was more frequent in adenocarcinomas with mucus‐producing component (P = 0.033) and micropapillary structure (P = 0.012)." (PMID 32729257, 2020). "In the ROS1-positive cohort, 21(95%) patients had adenocarcinoma histology, while 1(5%) patient had sarcomatoid adenocarcinoma as primary histology." (PMID 30915158, 2019).
adenocarcinoma (continued). "Further studies are warranted to validate these in a larger patient cohort and identify further markers of interest such as ROS1 and RET rearrangements, other EGFR mutants and in NRAS-, KRAS-mutated adenocarcinomas." (PMID 30889898, 2019). "Adenocarcinomas with CD74-ROS1 fusion, which is the most frequent fusion gene, usually shows globular cytoplasmic ROS1 immunoreactivity, whereas adenocarcinomas with EZR-ROS1 fusion usually show membranous immunostaining." (PMID 29538329, 2018). "ROS1-rearranged adenocarcinoma is clinicopathologically characterized by solid growth with signet-ring cells or a cribriform morphology with abundant extracellular mucus, and typically occurs in younger non-smoking females." (PMID 29538329, 2018). "ROS1 rearrangement was found in acinar (n=5), solid (n=4), lepidic (n=3) and papillary (n=1) adenocarcinoma." (PMID 28881815, 2017). "Detection of ROS1 protein expression in ROS1-positive adenocarcinomas with signet ring cells is challenging since the cytoplasm is largely replaced by non-reactive mucin." (PMID 27535289, 2016). "All the cases with ROS1 rearrangement were diagnosed as adenocarcinoma, and acinar pattern was the most predominant observed pattern." (PMID 27488371, 2016). "The predominant histology for ROS1-positive NSCLC is adenocarcinoma, although ROS1 has been found (infrequently) in large cell and squamous cell histologies." (PMID 29282427, 2016). "So we analyzed the 137 adenocarcinoma cases in this cohort and found that the enrichment of adenocarcinomas yielded greater frequency (2.9%) of ROS1 rearrangement compared with all NSCLC cases reported by previous studies." (PMID 25905642, 2015). "In resected stage IIIA-N2 NSCLC patients, ROS1-rearranged cases tended to occur in younger patients with adenocarcinomas." (PMID 25905642, 2015). "Multivariate analysis by Lee and colleagues showed that ROS1 expression was an independent factor for poor prognosis in cases with stage I adenocarcinoma." (PMID 25905642, 2015). "In resected stage IIIA-N2 NSCLC, ROS1-rearranged cases tended to occur in younger patients with adenocarcinomas." (PMID 25905642, 2015). "The prognosis of resected stage IIIA-N2 NSCLC is unsatisfactory, but the higher frequency of ROS1 rearrangement in stage IIIA-N2 adenocarcinoma cases reminds that targeted therapy will be a new treatment strategy." (PMID 25905642, 2015). "Adenocarcinoma cells were detected in the pericardial fluid, and ROS1 gene rearrangement was found on examination of the cell block prepared from the same pericardial effusion using next-generation sequencing (Oncomine Comprehensive Assay v3; Thermo Fisher Scientific, Waltham, MA)." (PMID 39559635, 2024). "In patients with adenocarcinoma, EGFR, ALK, and ROS1 mutations as well as PD-L1 expression were mostly tested using single biomarker assays, such as Sanger sequencing, reverse transcriptase-polymerase chain reaction, immunohistochemistry, and fluorescent in situ hybridization." (PMID 39518907, 2024). "The most prevalent alterations identified by RNA sequencing included fusions or exon skipping mutations involving therapy-associated genes MET (2.9%), ALK (1.7%), ROS1 (0.9%), and RET (0.7%), all of which were detected at a significantly higher frequency in adenocarcinoma cases." (PMID 39664186, 2024). "We hypothesize that the newly emerged ROS1 rearrangement occurs as the subset of cells harboring ROS1 gradually becomes the predominant pathological type of adenocarcinoma following pembrolizumab treatment." (PMID 39723367, 2024). "We hypothesize that the newly emerged ROS1 rearrangement occurs because the cell subset carrying ROS1 gradually becomes the predominant pathological type of adenocarcinoma following pembrolizumab treatment." (PMID 39723367, 2024). "The ROS1 prevalence in adenocarcinomas was 0.6% with our algorithm." (PMID 37237384, 2023).
adenocarcinoma (continued). "Currently, the prevalence of ROS1 fusion in late-stage disease in the Norwegian population is unknown, but as ROS1 testing has become mandatory in adenocarcinomas we will know more about this in the coming years." (PMID 37237384, 2023). "IR-guided liver biopsy confirmed adenocarcinoma with ROS1 rearrangement by NGS testing and FISH." (PMID 37923925, 2023). "The prevalence of ROS1 fusion in resected adenocarcinomas in this cohort was 0.6%." (PMID 37237384, 2023). "The mean age of the total population was 60.1 years old (range 32-77 years), patients (68.89%) were ≤65 years old, 55 patients (61.11%) were male, 75 patients (83.33%) were adenocarcinoma and 40 cases had gene mutation (31 were EGFR+,7 were ALK+, and 2 were ROS1+), 73(81.11%) patients with KPS ≥70." (PMID 37810984, 2023). "Moreover, we analyzed the clinicopathological features of adenocarcinomas with ROS1 translocation, its impact on survival and the objective response rate to crizotinib." (PMID 35628598, 2022). "In the case of adenocarcinoma, in particular, driver mutations and the corresponding drugs already exists and thus, it reacts well to targeted therapy, which includes, but is not limited to EGFR, ALK, and ROS1, resulting in good outcomes." (PMID 33422052, 2021). "Therefore, genetic testing, including at least EGFR mutations and ALK/ROS1 rearrangements, should be performed in all NSCLC patients (in particular with adenocarcinoma) who received a diagnosis of advanced disease." (PMID 34094913, 2021). "The purpose of this study was to investigate the differences in CT characteristics and disease spread patterns between ROS1-rearranged adenocarcinomas and epidermal growth factor receptor (EGFR)-mutant or anaplastic lymphoma kinase (ALK)-rearranged adenocarcinomas." (PMID 33005033, 2020). "ROS1 fusion was detected in five patients with adenocarcinoma." (PMID 32729257, 2020). "Concordant with previous molecular studies, major driver events in adenocarcinoma, namely EGFR activating mutations, ALK gene rearrangement and ROS1 gene rearrangement, were rarely present in pulmonary LELC, indicating that they were less important events in the pathogenesis of pulmonary LELC." (PMID 32726920, 2020). "For ALK and ROS1-rearrangement positive adenocarcinoma patients might experience more benefit to pemetrexed-based chemotherapy, molecular characteristics would have been desirable." (PMID 31088547, 2019). "This is in marked contrast to NSCLC, particularly adenocarcinoma, where genome sequencing efforts have revealed the identity of numerous recurrent, actionable somatic alterations, including oncogenic EGFR mutations, as well as ALK- and ROS1 rearrangements." (PMID 29138515, 2017). "With the development of targeted therapy, adenocarcinoma are classified into subsets, such as epidermal growth factor receptor (EGFR)-mutated type, anaplastic lymphoma kinase (ALK)-rearranged type and ROS1-rearranged type." (PMID 27708233, 2016). "In our study, a total of 4 cases with ROS1 rearrangement were all adenocarcinomas." (PMID 25905642, 2015). "Adenocarcinoma cases had a higher prevalence of SNVs, CNVs, and/or fusions/rearrangements in 28 genes including therapy-associated genes such as KRAS (37.5% vs 4.6%), EGFR (17.1% vs 1.3%), BRAF (5.2% vs 1%), ERBB2 (1.8% vs 0.8%), RET (0.9% vs 0.3%), and ROS1 (1.2% vs 0.1%)." (PMID 39664186, 2024). "Thus, the prevalence of ROS1 fusion was 0.6% in adenocarcinomas and 0.3% in the whole cohort." (PMID 37237384, 2023). "In addition, ROS1 fusions are more prevalent in adenocarcinomas than in other NSCLC histologies." (PMID 33435440, 2021). "ROS1 rearrangement is found in 1–3% of adenocarcinomas, with CD74-ROS1 fusion being the most common." (PMID 39513892, 2024). "Several biomarker-guided therapies have been approved, targeting genes frequently altered in adenocarcinoma, such as EGFR, BRAF, MET, ALK, ROS1, RET and NTRK." (PMID 39199558, 2024).
adenocarcinoma (continued). "In some NSCLC patients, mainly adenocarcinoma, molecular alterations in driver genes, like EGFR, KRAS, HER2, ALK, MET, BRAF, RET,ROS1, and NTRK are recognized." (PMID 37346803, 2023). "Adenocarcinomas harbor targetable genomic alterations in ALK, BRAF, EGFR, and ROS1 genes, and novel treatment options such as KRAS Gly12Cys, MET, NTRK, and RET inhibitors, and possibly ERBB2 guided therapies are broadening the clinical repertoire." (PMID 35964518, 2022). "In total, 140 out of 146 samples (96%) of adenocarcinoma were adequate for ALK, ROS1 and TPS PD‐L1 immunohistochemical assessment, and 137/146 (93.8%) were adequate for molecular profiling." (PMID 35868633, 2022). "Given the increasing number of treatment options, EGFR, ALK, ROS1 and BRAF testing is now required at the diagnosis of advanced adenocarcinoma to define the best first line treatment." (PMID 34884672, 2021). "A multivariable logistic regression model was applied to determine the clinical and CT characteristics that can discriminate between ROS1-rearranged and EGFR-mutant or ALK-rearranged adenocarcinomas." (PMID 33005033, 2020). "While the majority of tumors in all three molecular subgroups had adenocarcinoma histology, there was a higher frequency of neuroendocrine histology among RET+ tumors included in this study (RET: 12% vs ALK: 2%, p = 0.025; vs ROS1: 0%, p = 0.010)." (PMID 32183422, 2020). "In summary, despite shared clinical and imaging features, ROS1-, ALK-, and EGFR-positive advanced adenocarcinomas differ in certain imaging features of the primary tumor and disease spread patterns." (PMID 33005033, 2020). "The efficacy of first line pemetrexed-based chemotherapy was investigated in patients with HER2-mutant and those with EGFR-mutant, ALK/ROS1-rearranged and KRAS-mutant advanced adenocarcinomas." (PMID 29587667, 2018). "ROS1- and RET-rearranged adenocarcinomas have a similar histology to ALK-rearranged adenocarcinoma, such as mucinous cribriform pattern or solid signet-ring cell pattern." (PMID 28894699, 2017). "In EGFR and KRAS-wild type adenocarcinomas (EGFRwt/KRASwt), different potential drivers of pathogenesis exist, including ALK, RET, and ROS1 gene fusions, with ALK rearrangements being therapeutically relevant." (PMID 24205279, 2013). "A 39-year-old woman diagnosed with Stage IV adenocarcinoma of the left lung, negative for EGFR, ALK, and ROS-1, but with an ERBB2 mutation, experienced neurological symptoms leading to a diagnosis of brain metastasis in 2019." (PMID 41180730, 2025). "In patients diagnosed with adenocarcinoma or unspecified NSCLC without activating mutations in the EGFR gene, the status of the ALK and ROS1 genes should be evaluated to detect rearrangements that occur in 3–5% and 1% of patients, respectively." (PMID 40076671, 2025). "ROS1 rearrangements occur in 1–2.6% of NSCLC patients and are clinically associated with never-smoking history, younger age and adenocarcinoma histological type, frequently with brain metastases." (PMID 41153394, 2025). "A 39-year-old woman was diagnosed with Stage IV adenocarcinoma of the left lung, which tested negative for EGFR, ALK, and ROS-1 mutations, while showing a 2% expression of PD-L1 and an ERBB2 mutation." (PMID 41180730, 2025). "As an alternative algorithm, NTRK testing could be performed after histological confirmation of NSCLC and, in the case of adenocarcinoma, immunohistochemical exclusion of ALK or ROS1 alterations." (PMID 37296928, 2023). "The 10-year overall survival rate of the four ROS1-translocated adenocarcinoma patients was worse than that of patients without ROS1 translocation in the pre-crizotinib period (p < 0.0001)." (PMID 35628598, 2022). "Although IHC is the most user-friendly method for pathologists, some primary adenocarcinoma specimens were reported to have ROS1 expression without expressing the ROS1 translocation." (PMID 35628598, 2022).